NGF (nerve growth factor)
Diseases named in the same sentence as NGF in open-access papers (continued):
Sharing a sentence is not in itself a finding about the gene and the disease.
cystitis (continued). "We have also determined whether additional changes in neuropeptides/receptors and growth factors/receptors are observed in LUT pathways in NGF-OE treated with CYP to induce cystitis." (PMID 29255407, 2017). "Additionally, scavenging strategies involving sequestration of NGF or its receptor TrkA, as well as administration of Trk inhibitors, reduces urinary frequency in rodent models of urinary bladder inflammation." (PMID 29255407, 2017). "Thus it is likely that in cystitis the elevated level of NGF in the inflamed urinary bladder can increase BDNF expression in the DRG through retrograde transport." (PMID 24303055, 2013). "To examine whether NGF-induced Akt pathway had a role in NGF-induced BDNF expression during cystitis, we first compared the expression pattern of BDNF and p-Akt." (PMID 24303055, 2013). "To examine whether cystitis-induced BDNF up-regulation in L6 DRG was triggered by endogenous NGF in vivo, we administered a NGF neutralizing antibody to rats with cystitis to block NGF action." (PMID 24303055, 2013). "During cystitis or other visceral/peripheral inflammation, NGF is produced in the inflamed organ." (PMID 24303055, 2013). "Anti-NGF treatment reversed cystitis-induced bladder overactivity." (PMID 22742729, 2012). "To examine whether CGRP up-regulation in the L6 DRG was mediated by endogenous NGF during cystitis, we administered a NGF neutralizing antibody to rats with cystitis to block NGF activity in vivo." (PMID 22742729, 2012). "Since phospho-ERK5 was co-localized with CGRP in the L6 DRG during cystitis, we then examined whether NGF-induced CGRP in the DRG was mediated by the ERK5 pathway." (PMID 22742729, 2012). "Given that NGF actions during cystitis may be primarily TrkA-mediated, this finding is consistent with the understanding that p75NTR modulates NGF-TrkA actions when the two receptors are coexpressed, potentially even when activated by immature proneurotrophins." (PMID 37701182, 2022). "Furthermore, recent studies have demonstrated that BoNT-A has an anti-inflammatory effect on a cystitis rat model and that injection of BoNT-A can reduce the production of nerve growth factor in the bladder resulting in satisfactory pain relief in IC/PBS patients." (PMID 26999201, 2016). "NGF may play a role in regulating BDNF in sensory neurons in cystitis." (PMID 24303055, 2013). "This suggests that CREB may also be involved in NGF signaling during cystitis." (PMID 22742729, 2012). "Its sequestration via TrkA-IgG fusion molecules prevents the development of hyperalgesia, and treatment with the NGF-scavenging agent REN1820 reduces voiding frequency and pain behaviors in rats with CYP-induced cystitis." (PMID 37701183, 2023). "They observed increased NGF levels in the bladder, spinal cord, and lumbosacral dorsal root ganglia (DRG) in animals with spinal cord injury or chronic cystitis that exhibited bladder overactivity." (PMID 32028597, 2020). "Quantitative PCR was used to determine NGF, BDNF and receptors (TrkA, TrkB, p75NTR) and PACAP/VIP and receptors (PAC1, VPAC1, VPAC2) transcripts expression in LUT tissues from NGF-OE and WT mice with CYP-induced cystitis (4 h, 48 h, and chronic)." (PMID 29255407, 2017). "These in vivo and in vitro experiments indicated that NGF played an important role in the activation of Akt and subsequent up-regulation of BDNF in the sensory neurons in visceral inflammation such as cystitis." (PMID 24303055, 2013). "In the present study we show that sequestration of endogenous NGF in a cystitis rat model also blocks BDNF mRNA and protein levels in the DRG supporting a role of NGF in regulating BDNF expression in vivo." (PMID 24303055, 2013). "So far we have found that BDNF expression was regulated by endogenous NGF and also by PI3K-dependent Akt activation in L6 DRG during cystitis." (PMID 24303055, 2013).
cystitis (continued). "Blockade of NGF action in vivo reduces the number of DRG neurons co-expressing CGRP and phospho-CREB, and reverses cystitis-induced increases in micturition frequency." (PMID 22742729, 2012). "In the present study, we demonstrate that injection of NGF antibody reverses both the elevated levels of CGRP mRNA and protein in L6 DRG induced by cystitis." (PMID 22742729, 2012). "Taken together, these results suggest that NGF regulates sensory activity and CGRP expression involves CREB activation during cystitis." (PMID 22742729, 2012). "Women grappling with bladder dysfunction, encompassing idiopathic sensory urgency, chronic cystitis, and IC/BPS, manifested increased bladder NGF immunoreactivity in comparison to their counterparts without distressing symptoms, which included women with stress urinary incontinence." (PMID 37940904, 2023). "This expression disparity was also seen for NGF protein and mRNA levels after SCI-induced cystitis and was suggested to reflect retrograde axonal transport of NGF to the dorsal root ganglia, which may be related to altered lower urinary tract function." (PMID 32572272, 2020). "CRP/Crea and NGF/Crea values of dogs with cystitis were higher than in dogs without bacteria and/or leukocytes in the urine." (PMID 26746899, 2016). "Treatment with NGF neutralizing antibody also decreased the BDNF mRNA level in CYP-treated animals when compared to CYP+IgG treatment, suggesting that endogenous NGF elicited BDNF transcription in the L6 DRG during cystitis." (PMID 24303055, 2013). "Treatment with NGF neutralizing antibody also decreased the CGRP mRNA level in CYP-treated animals when compared to CYP + IgG treatment, suggesting that endogenous NGF triggered CGRP transcription in the L6 DRG during cystitis." (PMID 22742729, 2012). "The key findings of the present study are that activation of the ERK5 but not the Akt pathway is involved in cystitis- and retrograde NGF-induced CGRP expression in primary sensory neurons." (PMID 22742729, 2012). "Moreover, elevated levels of nerve growth factor (NGF) within the inflamed bladder and increased expression of neurotrophic factor receptors in bladder afferent neurons of rats with cystitis could provide a mechanism for mediating this effect on ERK signalling." (PMID 20035635, 2009). "Urine samples with bacteria and/or leukocytes had no significant increase in urinary NGF (p = 0.1112) or CRP (p = 0.0534) concentrations, but higher CRP-levels in urine from dogs with cystitis were found compared to dogs without signs of cystitis." (PMID 26746899, 2016). "Importantly, while it is possible to observe that, as in cystitis, SCI-induced NDO courses with high NGF levels, the same does not happen in MS models." (PMID 36834694, 2023).
memory impairment (25 papers, 2011 to 2025). "For example, degradation or neutralization of NGF, impaired NGF transport, lower TrkA density, or antagonists of TrkA reduce the cholinergic phenotype, and cause memory impairment." (PMID 31233568, 2019). "Heterozygous NGF knockout mice have reduced levels of NGF in the hippocampus, display memory impairment, show shrinkage and loss of cholinergic septal cells and have decreased cholinergic innervation of the hippocampus." (PMID 22654716, 2011). "NGF can inhibit neuronal oxidative stress, prevent neuronal loss, stimulate neurite outgrowth, and improve memory impairment." (PMID 34720898, 2021). "The very popular Bushen-Yizhi formula was noted, for example, to be able to regulate NGF signal transduction and the anti-apoptotic cholinergic pathway to improve memory impairment in an AD rat model." (PMID 35163136, 2022). "Taken together, the results of this study demonstrated that SS can prevent and protect against scopolamine-induced memory impairment by regulating the NGF-BDNF-CREB signaling pathway and inhibiting AChE expression." (PMID 30018265, 2018). "These alterations in the pro-NGF and/or NGF levels are related to attentional, learning, and memory impairments shown by ADHD patients." (PMID 28751869, 2017). "Numerous reports have also demonstrated that NGF administration improved learning and memory impairments in aged rats, coupled with a partial reversal of cholinergic neuron atrophy." (PMID 27119005, 2016). "Moreover, bioactive components of ginger 6-shogaol have increased the levels of NGF and improved scopolamine-induced memory impairment in animal models of dementia." (PMID 35163136, 2022). "To test this hypothesis, in this study, we took advantage of the availability of mouse models of AD (APP/PS1), which display memory impairment, and AD human samples to address the role of pro-NGF/p75NTR signaling in different aspects of adult neurogenesis." (PMID 34639085, 2021). "Additionally, treatment with GF diets increased nerve growth factor (NGF) levels in the brain and tempered the memory impairment in the animal model." (PMID 33396967, 2020). "As reported in some studies, NGF may prevent memory impairment and re-induce hippocampal neurotrophin expression of pneumococcal meningitis in rats." (PMID 33031061, 2020). "On the other hand, a conditional knockout of the NGF/TrkA axis in the young adult was not sufficient to cause learning/memory impairment." (PMID 31233568, 2019). "In addition, all of these studies were exclusively concerned with efficacy (NGF release: n = 2, hippocampal neurogenesis: n = 2, long-term potentiation: n = 1, short-term potentiation: n = 1, short-term memory: n = 1, or memory impairment: n = 2)." (PMID 29886845, 2018). "Early studies have reported that spatial learning and memory impairment could be reversed by NGF, which means that NGF also plays an important role in the learning and memory abilities." (PMID 29190943, 2017). "It is known that both NGF and BDNF have been found to enhance acetylcholine release, while deficiencies in acetylcholine release and BDNF or NGF expressions are related to memory impairment in AD patients, as mentioned in the introduction." (PMID 23651534, 2013). "KUT dose-dependently upregulated choline acetyltransferase (ChAT) activity and increased nerve growth factor (NGF) secretion in vitro, and improved passive avoidance behaviour and induced ChAT activity in the cerebral cortex of aged rats, and in scopolamine-induced memory impaired rats in vivo." (PMID 23445907, 2013). "Ni, Al and Ni/Al mixture exhibited memory impairment by activation of oxidative stress, COX-2, and diminution of AChE, BDNF and NGF levels in cerebral cortex and hippocampus." (PMID 37841055, 2023). "Taken together, the present results show that the nacre polysaccharide recovers scopolamine-induced memory impairment by increasing the expression of BDNF and NGF and showing antioxidant and anti-inflammatory activities." (PMID 33804892, 2021).
memory impairment (continued). "Moreover, CGA mitigated memory impairment and reversed the inhibition of the neurotrophic factors brain-derived neurotrophic factor (BDNF) and nerve growth factor (NGF), alleviating nerve injury." (PMID 36771496, 2023). "Thus, we examined the effect of EGFO extract on levels of CREB phosphorylation and NGF expression in both the hippocampus and cortex of mice brain with SCO-induced memory impairments." (PMID 31141948, 2019). "The memory impairments induced by Aβ1–42 were corrected with an intra-hippocampal infusion of BDNF, whereas NGF and NT-3 did not produce these effects." (PMID 25849905, 2015).
Allergy (24 papers, 2005 to 2025). An allergy is an immune response or reaction to substances that are usually not harmful. "High levels of NGF have been detected in the bronchoalveolar lavage fluids (BALF) and serum from asthmatic patients, suggesting that NGF is regulated in the airways and that NGF expression levels are associated with severity of the allergic disease." (PMID 24223654, 2013). "However, an increase in plasma NGF levels due to excess physical activity is also associated with the occurrence of a Th2 response in subjects with allergic diseases." (PMID 31396052, 2019). "NGF is increased in biologic fluids of allergy/immune-related diseases and has been evaluated as a TH2 cytokine with a modulator role in allergic inflammation and tissue remodeling." (PMID 27872863, 2016). "The most likely source of elevated serum NGF in allergy is from IgE-stimulated mast cells in tissues, since mast cells synthesize and secrete NGF." (PMID 25426119, 2014). "Discussing neuro-immune interaction at baseline in detail, an increase in NGF expression and in NF density can be observed in chronically inflamed skin and allergy." (PMID 25464511, 2014). "NGF acts as a local stress mediator in perceived stress and allergy and increased NGF messaging contributes to worsening of cutaneous inflammation." (PMID 24146927, 2013). "Allergen-induced epithelial-origin nerve growth factor (NGF) has been demonstrated to be involved in the early phase of allergic reactions." (PMID 24223644, 2013). "NGF has been considered to act as a local stress mediator in perceived stress and allergy and that increased NGF message contributes to worsening of cutaneous inflammation." (PMID 23028581, 2012). "Increased levels of eosinophil have been linked to allergic reactions.Similarly, patients positive for nerve growth factor have been reported to have a significantly higher number of eosinophil, whichplay an important role in allergies and respiratory diseases." (PMID 37886149, 2023). "In a previous study, we demonstrated that exposure to toluene, a volatile organic compound, aggravated airway inflammatory responses in a mouse model of allergy by modulating the number of inflammatory cells and enhancing the plasma levels of nerve growth factor (NGF)." (PMID 31597243, 2019). "The mechanisms by which NGF may be involved in allergic disease or in comorbid disease of allergy and ADHD are unknown, but a small number of theories have been postulated." (PMID 27872863, 2016). "The differentiation of human mast cell subtypes that could perpetuate human allergic reactions is dependent on NGF." (PMID 27872863, 2016). "The medical records of patients with IC/BPS were reviewed to reveal if a higher serum NGF level might appear in patients with autoimmune or allergic disease." (PMID 23028581, 2012). "It is notable that plasma levels of NGF are significantly higher in patients with vernal keratoconjunctivitis compared to healthy controls whereby NGF modulates the synthesis of substance P (SP), a neuropeptide involved in the pathogenesis of human allergic diseases." (PMID 40422222, 2025). "The inhibitory effects of XQLT on NGF, p75NTR and TSLP may be associated with the TLR4 pathway, thus providing pharmacological targets for investigations into how XQLT affects the early phase of allergic reactions." (PMID 24223644, 2013). "Moreover, NGF has been observed at an elevated concentration in patients with allergic diseases." (PMID 24223644, 2013). "Apart from the extensive studies of NGF and BDNF in allergic rhinitis and atopic dermatitis, the reports regarding the other genes related to neurogenic inflammation in allergies are limited and focused mainly on adult populations of patients." (PMID 32596360, 2020). "NGF promotes the TLR4 signaling-induced maturation of DCs through inducible p75NTR, an important event in allergy initiation." (PMID 24223644, 2013).
Allergy (continued). "Increased expression of neurotrophin-3 and neurotrophin-4 was previously reported in allergies by several papers, although they were not studied as extensively as NGF or BDNF." (PMID 32596360, 2020). "Indeed, IL-10 release by immune cells, which is enhanced by both NGF and BDNF in normal conditions, is dramatically reduced in cases of allergy." (PMID 24223945, 2013). "Moreover, NGF and BDNF have been observed at elevated concentration in patients with allergic diseases." (PMID 24010817, 2013). "In conclusion, XQLT may regulate NGF, p75NTR and TSLP via the TLR4 pathway in the early phase of an allergic reaction." (PMID 24223644, 2013).
injury (24 papers, 2010 to 2025). Damage inflicted on the body as the direct or indirect result of an external force, with or without disruption of structural continuity. "Given that upregulation of BDNF and NGF in the dorsal horn after nerve injury is associated with an enhanced pro-inflammatory response and hyperalgesia, these findings are indicative of a normalization of neurotrophic levels in response to exercise, resulting in an anti-inflammatory response." (PMID 37138291, 2023). "In recent years, growing interest has focused on the potential therapeutic benefits of neurotrophic factors, specifically nerve growth factor (NGF), in promoting recovery following brain injury." (PMID 40573325, 2025). "The large molecular weight and limited permeability of mouse‐derived nerve growth factor (mNGF) across the blood–brain barrier (BBB) have restricted its therapeutic use after brain injury." (PMID 41039850, 2025). "The authors show that BDNF and NGF levels are significantly higher in the cerebrospinal fluid and plasma of children with severe traumatic brain injury, compared to the control group." (PMID 32987792, 2020). "The role of neuropeptides such as nerve growth factor (NGF) in controlling this nerve overgrowth was described in experimental skin injury and is supported by the clinical evidence of keratoconus progression after injury-induced fifth nerve palsy." (PMID 26495846, 2015). "NGF has been shown to be elevated in cerebrospinal fluid of children following traumatic brain injury." (PMID 20507613, 2010). "The intricate relationship between nerve growth factor (NGF) and brain damage has been the subject of extensive research, with studies elucidating the role of NGF in promoting neural recovery and plasticity after brain injury." (PMID 40951886, 2025). "Nerve growth factor, the first discovered neurotrophic factor, plays a pivotal role in maintaining neuronal survival, growth, differentiation, and facilitating repair and regeneration after nerve injury." (PMID 40771933, 2025). "Intranasal treatment with NGF has also been tested on children, obtaining remarkable outcomes as well since, to date, there are no therapeutic strategies in children affected by severe traumatic brain injury, and the only applicable therapy is palliative." (PMID 39056738, 2024). "Indeed, the safety and usefulness of nasal administration of NGF-based treatments were described in a child with severe traumatic brain injury." (PMID 36899901, 2023). "There are several hypotheses to explain why NGF exerts beneficial effects in traumatic brain injury." (PMID 37789391, 2023). "Thus, given the role of NGF in promoting pain, MaR1 is much better for the treatment of nerve injury." (PMID 35109876, 2022). "Hence, NGF can protect against post-ischemic dysfunction of sympathetic innervations and ischemia-reperfusion myocardial injury." (PMID 21085492, 2010). "Rat nerve growth factor and total flavonoids from hawthorn leaf contribute to the recovery of neurological function after spinal cord injury, including traumatic, non-traumatic spinal cord injuries." (PMID 40817719, 2025). "Furthermore, NGF is also involved in sympathetic sprouting at the DRG level, as anti-NGF injection reduced this condition and alleviated neuropathic pain after nerve injury." (PMID 41301953, 2025). "It is known that IL-4 and IL-5 can increase the amount of nerve growth factor, which is secreted by astrocytes after neural trauma, independent of cell growth." (PMID 38334617, 2024). "However, we found increased artemin synthesis in the peripheral tissue after inflammation or nerve injury, which may have an important role in the regulation of TRP channel expression, as is the case with NGF." (PMID 25889103, 2015).
injury (continued). "Concerning nerve growth factor (NGF), we observed a high and statistically significant increase of its expression in MSC-grafted animals compared to controls, which totally agrees with the results obtained after MSC iv transplantation in traumatic brain injury." (PMID 22745769, 2012).